CASQ1 (calsequestrin 1)
Description:
Calsequestrin is a high-capacity, moderate affinity, calcium-binding protein and thus acts as an internal calcium store in muscle. Calcium ions are bound by clusters of acidic residues at the protein surface, often at the interface between subunits. Can bind around 80 Ca(2+) ions. Regulates the release of lumenal Ca(2+) via the calcium release channel RYR1; this plays an important role in triggering muscle contraction. Negatively regulates store-operated Ca(2+) entry (SOCE) activity.
Synonyms: CASQ; PDIB1; CSQ1; VMCQA
Tractability: Antibody: UniProt places it where antibodies can reach, with medium confidence; UniProt predicts a signal peptide or a membrane-spanning region; its Gene Ontology location is reachable by antibodies, with medium confidence.
Gene: Protein-coding gene on chromosome 1 (160,190,385 to 160,201,886, forward strand). Ensembl gene ENSG00000143318.
Subcellular location: Endoplasmic reticulum; Sarcoplasmic reticulum; Sarcoplasmic reticulum lumen; Sarcoplasmic reticulum membrane; Mitochondrion matrix
Subcellular location (Human Protein Atlas): Mitochondria; Nucleoplasm
Pathways (Reactome):
Muscle contraction: Ion homeostasis
Transport of small molecules: Stimuli-sensing channels
Gene Ontology:
Molecular function: calcium ion binding; identical protein binding; protein binding
Biological process: positive regulation of release of sequestered calcium ion into cytosol; positive regulation of store-operated calcium channel activity; protein polymerization; regulation of store-operated calcium entry; regulation of skeletal muscle contraction by regulation of release of sequestered calcium ion; sarcomere organization; regulation of release of sequestered calcium ion into cytosol; response to denervation involved in regulation of muscle adaptation; response to muscle inactivity; skeletal muscle tissue development
Cellular component: endoplasmic reticulum; mitochondrion; sarcoplasmic reticulum; mitochondrial matrix; sarcoplasmic reticulum lumen; sarcoplasmic reticulum membrane; smooth endoplasmic reticulum; Z disc; I band; junctional sarcoplasmic reticulum membrane; myofibril; sarcolemma; T-tubule; terminal cisterna; terminal cisterna lumen
Genetic constraint (gnomAD): Loss-of-function variants: 22 observed, 32.54 expected, observed/expected ratio (o/e) 0.68, 90% interval 0.48 to 0.96. The upper end of that interval is the gene's LOEUF score, 0.96, which puts it in group 4 of 6, group 1 being the genes least tolerant of losing a copy. Missense variants: 391 observed, 413.91 expected, observed/expected ratio (o/e) 0.94, 90% interval 0.87 to 1.03. Synonymous variants: 146 observed, 162.32 expected, observed/expected ratio (o/e) 0.9, 90% interval 0.79 to 1.03.
Homologues: Orthologues: chimpanzee CASQ1 (99% identical), macaque CASQ1 (99% identical), rat Casq1 (96% identical), mouse Casq1 (95% identical), pig CASQ1 (95% identical), rabbit CASQ1 (93% identical), guinea pig CASQ1 (93% identical), tropical clawed frog casq1 (78% identical), dog CASQ1 (76% identical), zebrafish casq1a (62% identical), zebrafish casq1b (61% identical), Caenorhabditis elegans csq-1 (32% identical). Paralogues in human: CASQ2 (62% identical).
Diseases named in the same sentence as CASQ1 in open-access papers:
CASQ1 is named in the same sentence as 46 diseases in open-access papers, as found by Europe PMC text mining. Sharing a sentence is not in itself a finding about the gene and the disease. The quoted sentences say what the papers report.
Malignant hyperthermia (7 papers, 2016 to 2025). Malignant hyperthermia is characterized by a rapid increase in temperature to 39-42 degrees C. Malignant hyperthermia may occur in response to either inhalational anesthetics such as halothane, to muscle relaxants such as succinylcholine, or to exercise. "CASQ1 deficiency has been linked to malignant hyperthermia (MH) and exercise heat stroke (EHS)-like responses." (PMID 40725470, 2025). "CASQ1 ablation was found to alter muscle contractility and increase susceptibility to spontaneous mortality and heat/anesthesia-induced malignant hyperthermia-like episodes." (PMID 36746942, 2023). "This strategy was previously used to successfully reduce the formation of cores and susceptibility to malignant hyperthermia in mice carrying the human Y522S mutation in the RYR1 (YS mice) and in CASQ1-null mice." (PMID 41009681, 2025). "CASQ1-knockout mice and mice carrying a mutation in RYR1 (Y522S) linked to human malignant hyperthermia susceptibility (MHS) both suffer lethal hypermetabolic episodes when exposed to halothane (MHS crises) and to environmental heat (heat stroke, HS)." (PMID 36010545, 2022).
tubular aggregate myopathy (5 papers, 2020 to 2024). Tubular aggregate myopathy is a disorder that affects the skeletal muscles. "Mutations in the CASQ1 gene have been identified in patients affected by a rare vacuolar myopathy and in patients with tubular Aggregate Myopathy, TAM." (PMID 35454077, 2022). "Mutations in Orai1 and STIM1 have been identified in patients with tubular aggregate myopathy (TAM), a rare genetic disease characterized by accumulation, in type-2 fibers, of highly ordered membrane tubules containing SR proteins, such as CASQ1, SERCA, triadin, RyR1, and STIM1." (PMID 35454077, 2022).
vacuolar myopathy (4 papers, 2015 to 2025). "In this report, a dominant missense mutation in CASQ1 (N244G) was found in a group of patients with a vacuolar myopathy characterized by weakness, fatigue, and the presence of electron-dense inclusions." (PMID 26075051, 2015). "Mutant Casq1 in human patients has been linked to vacuolar myopathy." (PMID 35167494, 2022). "Variants in CASQ1 (MIM ID *114250, cytogenetic location 1q23.2) are a known cause of vacuolar myopathy with CASQ1 aggregates (MIM ID #616231)." (PMID 41313434, 2025). "Interestingly, mice knock-in for the CASQ1Asp244Gly, the CASQ1 mutation identified in patients with vacuolar myopathy, did not display any difference in SOCE compared to wild type mice." (PMID 39126637, 2024). "However, the degree to which mitochondrial alterations are observed in muscle biopsies from CASQ1 N244G vacuolar myopathy patients is currently unknown." (PMID 26075051, 2015).
cardiomyopathy (3 papers, 2010 to 2025). A disease of the heart muscle or myocardium proper. "Additionally, some of the dysregulated genes could potentially explain conditions and endophenotypes associated with dystrophin deficiency, such as dysregulation of calcium homeostasis (Pvalb and Casq1), or cardiomyopathy (Obscurin, Tcap)." (PMID 20515474, 2010).
Graves disease (3 papers, 2015 to 2020). Graves' disease is an autoimmune disorder that leads to overactivity of the thyroid gland (hyperthyroidism).It is caused by an abnormal immune system response that causes the thyroid gland to produce too much thyroid hormones. "In addition, a recent paper found that polymorphisms in calsequestrin (CASQ1) are correlated with HT and GO, but not Graves’ hyperthyroiditis (GH)." (PMID 27556446, 2016). "Unlike normal subjects, patients with Graves’ hyperthyroidism without ophthalmopathy and Hashimoto’s thyroiditis with or without ophthalmopathy show significant levels of autoantibodies against CASQ1 in the serum." (PMID 33288873, 2020).
Myalgia (2 papers, 2020 to 2025). "The phenotype, which did not include cramps or myalgia, was less typical for a CASQ1 myopathy, but some cases with severe progressive weakness and muscular dystrophy as the main findings have been described previously." (PMID 41313434, 2025). "As calsequestrin expression is restricted to skeletal muscle, patients with CASQ1 mutations show a mild form of TAM/STRMK with late-onset muscle weakness, myalgia, and abundant tubular aggregates, but without additional multi-systemic signs." (PMID 33250786, 2020).
thyroid autoimmunity (2 papers, 2012 to 2015). "In the present study we determined the prevalence of CASQ1 and collagen XIII antibodies in serum from probands and first or second degree relatives of a single family with multiple cases of thyroid autoimmunity." (PMID 22742084, 2012). "Of the four euthyroid relatives with positive eye muscle antibody tests only two (one with reactivity against CASQ1, WH-41, and one with reactivity against collagen XIII, WH-29) were first-degree relatives of probands with autoimmune thyroid disease." (PMID 22742084, 2012).
type 2 diabete (2 papers, 2008 to 2020). "Polymorphisms in the CASQ1 gene are found in the Caucasian population in North America and in the Amish population with type 2 diabetes, suggesting that sequence variation in the CASQ1 gene could increase the risk for type 2 diabetes." (PMID 33288873, 2020).
migraine (1 paper, 2007). "Six markers localised to the C1q23-C1q31 region covering several genes of interest (ATP1A4, CASQ1, KCNJ9 and J10, FasL and CACNA1E), have been analysed in regard to their potential association with migraine in a large population (243 migraineurs versus 243 healthy individuals)." (PMID 17727731, 2007).
muscle degeneration (1 paper, 2013). "Fewer (6 proteins; myosin-4, calsequestrin 1, ATP-citrate synthase, glycerol-3-phosphate dehydrogenase, fructose bisphosphate aldolase A, reticulon-4-interacting protein 1) were increased in control DIA and in the mdx EOM (which do not show muscle degeneration)." (PMID 23823696, 2013).
myonecrosis (1 paper, 2013). "The calcium-handling proteins sarcalumenin and calsequestrin-1 were increased in control EOM compared with control DIA, reinforcing the view that constitutional properties of EOM are important for their protection against myonecrosis." (PMID 23823696, 2013).
rhabdomyolysis (1 paper, 2022). Necrosis or disintegration of skeletal muscle often followed by myoglobinuria. "CASQ1 is a high affinity calcium storage protein in the sarcoplasmic reticulum that was a ↑DEP and ↓DEG in RER-susceptible Thoroughbred mares and a ↓DEG in RER-susceptible Thoroughbred geldings between episodes of rhabdomyolysis in previous studies." (PMID 36292738, 2022).
thyroid (1 paper, 2021). "As thyroid autoantibodies are known to play a role in pathogenesis and severity of TED14–16, other autoantibodies such as anti-calsequestrin 1 antibody (Anti-CASQ1 Ab) and anti-collagen XIII antibody (anti-COLXIII Ab) are also reported to be associated with the pathogenesis of TED17,18." (PMID 34215786, 2021).
myopathy (13 papers, 2015 to 2025). A disease of the muscle in which the muscle fibers do not function properly. "D244G (a heterozygous missense mutation in the CASQ1 gene) was the first identified CASQ1 mutant in patients showing mild myopathy characterized by muscle weakness, fatigue, and the presence of large vacuoles." (PMID 33288873, 2020). "Nevertheless, data of our study show that CASQ1 deficiency results in an age-dependent myopathy characterized by mitochondrial damage and formation of unstructured/contracture cores resembling those described in muscle biopsies from human CCD patients and in other mouse models of MH and CCD." (PMID 26075051, 2015). "Widened TC lumen and tubular aggregates within the lumen are a common feature in CASQ1-related myopathy, but to the best of our knowledge, this is the first report of morphologically altered SR-feet." (PMID 41313434, 2025). "Defects in other Ca2+ channel subunits including the voltage-gated Cav1.1 channel, calsequestrin 1 (CASQ1), stomal interaction molecule 1 (STIM1), and Ca2+ release-activated Ca2+ modulator 1 (ORAI1) have all been linked to myopathies." (PMID 35001666, 2022). "Second, it was reported that in human patients affected by a mild myopathy, an excess of Casq1 protein formed inclusions in the vacuoles; this condition was named Casq storage myopathy." (PMID 35167494, 2022). "Accordingly, these data suggest that RYR1 should be considered for genetic analysis in a myopathy with TA where STIM1, ORAI1 and CASQ1 mutations have been excluded." (PMID 35666680, 2022). "Specifically, we demonstrate that CASQ1-null mice develop a myopathy characterized by mitochondrial damage at early ages that precede the development of structural and contracture cores at later ages." (PMID 26075051, 2015). "The mother developed mild proximal muscle weakness and minor fatty replacement in the quadriceps muscles, which may be due to longer progression of the CASQ1-related myopathy." (PMID 41313434, 2025). "As a new feature of CASQ1-related myopathy, there were morphological changes in the SR-feet." (PMID 41313434, 2025). "In addition, a novel pathway was implicated in myopathies with the discovery of pathogenic variants in STIM1, ORAI1, and CASQ1 that are key players of Ca2+ homeostasis through the SOCE mechanism." (PMID 38982518, 2024). "Importantly, we demonstrated a central role for increased oxidative stress in the mitochondrial damage and myopathy by rescuing multiple phenotypes in CASQ1-null mice with anti-oxidant treatment." (PMID 26075051, 2015). "Since CASQ1 exhibits an MHS-like phenotype and MHS occurs in some CCD patients, we hypothesized that CASQ1-null mice may develop a myopathy resembling CCD." (PMID 26075051, 2015). "However, paralogs of myopathy genes are often expressed in different tissues, such as RYR1 and CASQ1, which are expressed in skeletal muscles, whereas RYR2 and CASQ2 are expressed in cardiac muscles." (PMID 39945189, 2025). "Here, we report on the identification of causative dominant RYR1 variants in two patients with a history of myopathy characterized by the presence of tubular aggregates in muscle biopsy and negative for mutations in STIM11, ORAI1 and CASQ1." (PMID 35666680, 2022).
cancer (4 papers, 2015 to 2024). A tumor composed of atypical neoplastic, often pleomorphic cells that invade other tissues. "However, no study has reported on the correlation between CASQ1 and cancer, a topic that requires further study." (PMID 32301283, 2020).
tumor (4 papers, 2020 to 2022). "Indeed, several downstream targets of MEF2 involved in muscle structure and function were among the top FoxP1 target genes repressed in response to tumour burden, including Casq1, Casq2, Lmod3, Ky, and Mef2c —suggesting that FoxP1 up‐regulation disrupts MEF2 transcriptional activity." (PMID 33527776, 2021). "The patient-based analysis identified one additional significant gene, ZNF845 (Padj = 2.6 × 10−2), whereas the tumor-based analysis identified four, TNRC6B (Padj = 2.9 × 10−4), ZNF780B (Padj = 4.2 × 10−2), RPP30 (Padj = 6.4 × 10−2), and CASQ1 (Padj = 8.7 × 10−2)." (PMID 35922826, 2022).
CASQ1 also shares sentences with these, for which no sentence is quoted: catecholaminergic polymorphic ventricular tachycardia (3 papers); Arrhythmia (2); Central core disease (2); Heat Stroke (2); cardiac diseases (1); coronavirus disease 2019 (1); degenerative diseases (1); diabetes (1); Duchenne muscular dystrophy (1); dystrophin deficiency (1); glioblastoma (1); glioma (1); Hashimoto disease (1); hearing loss (1); Hyperthermia (1); muscular disease (1); muscular disorders (1); muscular dystrophy (1); myocardial infarction (1); myocardial ischemia (1); neuromuscular genetic disease (1); Norum disease (1); sarcopenia (1); skeletal myopathies (1); Stormorken syndrome (1); Stroke (1); Timothy syndrome (1); Ventricular arrhythmia (1); ventricular tachycardia (1); viral myocarditis (1).